ABI3 (ABI family member 3)
Diseases named in the same sentence as ABI3 in open-access papers (continued):
Sharing a sentence is not in itself a finding about the gene and the disease.
tumor (continued). "Ectopic expression of ABI3 was sufficient to lead to a lower transforming activity, reduced tumor in vitro growth properties, suppressed in vitro anchorage-independent growth and in vivo tumor formation while, cellular senescence increased." (PMID 21223585, 2011). "Additionally, Tumor Immune Single-cell Hub (TISCH) database was consulted to determine the primary cell types expressing ABI3 in cancer microenvironments." (PMID 37942289, 2023). "Additionally, we conducted pan-cancer genomic alteration and prognostic assessments of ABI3, exploring potential links with CNV, DNA methylation, microsatellite instability (MSI), tumor mutational burden (TMB), and immune infiltration in neoplasms." (PMID 37942289, 2023). "Interpretation: Our study reveals that ABI3 acts as a robust tumor biomarker." (PMID 37942289, 2023). "Although ABI3 plays an important role as a tumor suppressor, the precise mechanism by which ABI3 exerts this function is still unknown." (PMID 36926204, 2023). "While the study of the role of ABI3 in cancer has been intensified, the precise mechanism by which ABI3 exerts its tumor-suppressive effect and/or cytoskeleton remodeling in thyroid cells is still unknown." (PMID 28978070, 2017). "Although our findings provide evidences to support classification of ABI3 as a bona fide tumor suppressor gene, the precise mechanism by which ABI3 exerts its function is still unknown." (PMID 28978070, 2017). "In addition to its tumor suppressive effect, it has been proposed that ABI3 is involved in tumor progression." (PMID 27036019, 2016). "Mounting evidence has indicated that ABI3 (ABI family member 3) function as a tumor suppressor gene, although the molecular mechanism by which ABI3 acts remains largely unknown." (PMID 21223585, 2011). "A more detailed understanding of the pathway by which ABI3 contribute to senescence may lead to the development of novel agents that can suppress tumor development." (PMID 21223585, 2011). "In summary, our results indicate that ABI3 expression plays an important role in suppressing tumor growth and progression, given that its expression was significantly lower in malignant specimens compared to benign lesions and ectopic expression reduced the transforming phenotype of both cell lines." (PMID 21223585, 2011). "Thus, we postulate that ABI3 may operate in LGG patients by adjusting the quantity of M2 macrophages in the tumor microenvironment, which further contributes to a worse prognosis." (PMID 37942289, 2023). "As each component of the WRC complex appears exchangeable, identifying members that directly interact with ABI3 and the pathway that may control these interactions can provide an important framework for understating the role of ABI3 in tumor initiation and progression." (PMID 28978070, 2017). "Moreover, ABI3 expression inhibited tumor formation in athymic mice." (PMID 27036019, 2016). "In IGHV-unmutated cases, they reported methylation of known or potent tumor suppressor genes (for example, VHL, ABI3, and IGSF4) as well as unmethylated genes involved in cell growth and tumor progression (ADORA3 and PRF1)." (PMID 38435839, 2024). "To determine the primary cell types expressing ABI3 in tumor microenvironment (TME), we conducted a single-cell analysis of ABI3 in 77 single-cell datasets of cancer samples." (PMID 37942289, 2023). "Although ABI3 had been found to modulate the advancement of diverse neoplasms, there is no comprehensive pan-cancer analysis of its effects." (PMID 37942289, 2023). "ARO cells expressing ABI3 did not form tumors in nude mice (n = 3) or formed a very small tumor (0.65 ± 1.17 cm3; n = 5)." (PMID 21223585, 2011). "The mechanistic basis by which ABI3 exerts its tumor suppressive effects is not fully understood." (PMID 28978070, 2017).
cancer (9 papers, 2011 to 2026). A tumor composed of atypical neoplastic, often pleomorphic cells that invade other tissues. "Our analysis of various indicators, including OS, DSS, DFI, and PFS, consistently revealed that ABI3 was profoundly linked to cancer patient prognoses." (PMID 37942289, 2023). "The protein encoded by the ABI3 gene was implicated in impeding cancer cell dissemination and motility, potentially via interactions with essential intracellular entities, such as PAK, which play a role in cellular motility." (PMID 37942289, 2023). "Nevertheless, we also identified that ABI3 was aberrantly upregulated in 14 types of cancer, which contradicts the previous notion that its expression was decreased in invasive malignancies, suggesting underlying functions of ABI3 across multiple cancer types." (PMID 37942289, 2023). "Loss of ABI3 expression was reported in several cancer cell lines, including a highly metastatic U87 human glioma cell line." (PMID 27036019, 2016). "ABI3 expression was linked to immunotherapeutic biomarkers and response in cancers." (PMID 37942289, 2023). "TIMER2.0 was leveraged to probe the immune cell infiltrations associated with ABI3 across cancers." (PMID 37942289, 2023). "We demonstrated that FAT10 induced cancer cell migration by preferentially stabilizing phosphorylated ABI3." (PMID 36926204, 2023). "Our investigation demonstrated that ABI3 expression manifested a correlation with TMB in 16 cancer classifications and with MSI in 9 cancer classifications." (PMID 37942289, 2023). "The cBioPortal database reveals that the frequency of ABI3 alterations was highest among pan-cancer patients with BRCA." (PMID 37942289, 2023). "To investigate the functional roles of ABI3 in cancers, we performed sequential functional enrichment analyses." (PMID 37942289, 2023). "Numerous studies have substantiated the robustly correlation between ABI3 expression levels and cancer onset and progression." (PMID 37942289, 2023). "We obtained 74 dysregulated SRGs between normal and cancer tissues, among which six genes (RPS6KA6, ABI3, PTTG1, E2F1, CBX7, and SPOP) were associated with the OS of CC patients." (PMID 37768206, 2023). "This investigation highlights the crucial role of ABI3 in tumorigenesis and metastasis, as well as its impact on the immunological and metabolic activity of malignant tumors." (PMID 37942289, 2023). "In conclusion, through multi-omics analyses of ABI3 across various cancer types, we identified it as a promising prognostic indicator." (PMID 37942289, 2023). "groups and examined the survival differences between CNV and the wide type of ABI3 gene in each cancer." (PMID 37942289, 2023). "Among the ABI family members, ABI3 has been extensively studied and shown to significantly impact cancer progression." (PMID 37942289, 2023). "The samples were stratified based on the median ABI3 expression in each cancer type, and bifurcated into low and high-ABI3 groups for GSEA and GSVA to discern the biological processes associated with ABI3." (PMID 37942289, 2023). "Our analysis revealed that the frequency of ABI3 alterations varied across pan-cancer, with the highest prevalence of copy number alterations observed in BRCA, MESO, and UCS, where the majority of cases were amplifications." (PMID 37942289, 2023). "Considering that FAT10 is overexpressed in various cancers and stabilizes phosphorylated ABI3, it is possible that the interaction between FAT10 and phosphorylated ABI3 contributes to cancer development." (PMID 36926204, 2023). "Subsequently, we employed TIMER2.0 to analyze ABI3 mRNA level differences between cancer and adjacent normal tissues." (PMID 37942289, 2023). "One of the significant outcomes of our study was the robust correlation between ABI3 expression and immune infiltration among various cancer types." (PMID 37942289, 2023). "ABI3BP is a potential partner of ABI3, and previous studies have shown that their expression levels are synchronized during cancer progression." (PMID 37942289, 2023).
cancer (continued). "We examined the genomic alterations in the ABI3 gene across different cancer types through the cBioPortal database." (PMID 37942289, 2023). "Overall, ABI3 was among the most comprehensively investigated ABI family members in the context of cancer progression." (PMID 37942289, 2023). "Ultimately, these findings suggest that increased ABI3 expression was associated with the immune-activated condition of malignancies and may be involved in the regulation of telomerase or DNA-related functions, ultimately influencing processes such as cancer initiation and progression." (PMID 37942289, 2023). "The pie chart shows a global profile that displays the constitution of the heterozygous/homozygous CNV of the ABI3 gene in each cancer, with different colors representing different CNV types." (PMID 37942289, 2023). "ABI3 has been identified as a component of WASP-family verprolin homologous protein (WAVE) regulatory complex in several cancer cells." (PMID 34731000, 2021). "Our study shows that the transcriptional silencing of ABI3 in cancer cells occurs via methylation and uncovered a previously unrecognized role for NKX2-1 in the regulation of ABI3." (PMID 27036019, 2016). "It has been shown that ABI3 expression is lost in invasive cancer cell lines, despite its ubiquitous expression in normal tissues." (PMID 21223585, 2011). "Our results indicate that ABI3 expression plays an important role in the pathogenesis and the progression of several cancers." (PMID 21223585, 2011). "To determine the effects of the ABI3 on transformation of human cancer cells we first determined the effects of ABI3 on cells growth in a focus formation assay." (PMID 21223585, 2011). "We not only observed that ABI3 expression is reduced or lost in most carcinomas but also that there is a positive correlation between ABI3 and ABI3BP expression." (PMID 21223585, 2011). "Univariate Cox regression approach was leveraged to evaluate ABI3’s prognostic role across cancers." (PMID 37942289, 2023). "The interaction between FAT10 and the phosphorylated form of ABI3 promoted cancer cell migration." (PMID 36926204, 2023). "Our results demonstrated that ABI3 served as a reliable prognostic biomarker for pan-cancer." (PMID 37942289, 2023). "In the HPA database, protein expression of ABI3 was only examined for two types of cancer." (PMID 37942289, 2023). "In this study, we hypothesized that FAT10 may regulate ABI3 through interaction, which contributes to cancer development." (PMID 36926204, 2023). "Additionally, we present the outcomes of the ABI3 pan-cancer CNV and methylation analysis in the GSCA database." (PMID 37942289, 2023). "Following this, we investigated the relationship between ABI3 and cancer patient prognosis." (PMID 37942289, 2023). "Moreover, our investigation offers supplementary perspectives on the wider applicability of ABI3 in tumors and verifies that ABI3 expression was intimately connected to immune cells and immune-related molecules across the majority of cancers." (PMID 37942289, 2023). "However, when FAT10 was overexpressed with wild-type ABI3 or its mutants, the wild-type or phospho-mimetic mutant of ABI3 promoted cancer cell migration, which was inhibited by the phospho-dead mutant." (PMID 36926204, 2023). "ABI3 may play a unique role as a critical regulator of Rac-mediated actin polymerization, which is involved in cellular motility and impacts cancer aggressiveness and metastasis." (PMID 37942289, 2023). "Subsequently, we conducted a screening for potential anti-cancer drugs that may exert their therapeutic effects through the action of ABI3." (PMID 37942289, 2023). "However, further studies on additional cohorts are needed to comprehensively evaluate ABI3’s value as an immunotherapy biomarker in cancer treatment." (PMID 37942289, 2023). "This research paves the way for further exploration of ABI3’s role in cancer immunity." (PMID 37942289, 2023).
cancer (continued). "Conversely, ABI3 expression manifested a negative association with the infiltration levels of progenitors of lymphoid and MDSCs in majority TCGA cancers, especially in BRCA and UCEC." (PMID 37942289, 2023). "Additionally, we downloaded the Expression Public 22Q4 file of ABI3 from the CCLE database to examine differences in ABI3 expression levels in 29 tissues based on the tissue source of the cancer cells." (PMID 37942289, 2023). "Our findings suggest that ABI3 is critically involved in anticipating cancer patient survival rates and could perform as a reliable indicator for prognosis for cancer patients." (PMID 37942289, 2023). "Although the molecular and functional characteristics of ABI3 have been studied in a few cancer cell culture models, its physiological role in the brain, especially in microglia, and the mechanisms by which ABI3 contributes to the etiology of AD are unknown." (PMID 34731000, 2021). "As hypermethylation of gene-associated CpG islands are mostly linked to transcriptional silencing of tumor suppressor gene in cancer, we used in silico analysis to identify CpG islands spread over 10,000 pb upstream and 500 bp downstream of the translation start site of the ABI3 gene." (PMID 27036019, 2016). "Our result links ABI3 to the pathogenesis and progression of some cancers and suggests that ABI3 or its pathway might have interest as therapeutic target." (PMID 21223585, 2011). "The identification of molecular events in the ABI3 pathway that control processes such as senescence, migration and invasion may suggest new therapeutic strategies for cancer." (PMID 21223585, 2011). "Although these reports indicate that ABI3 loss may play a role in the pathogenesis and/or progression of certain cancers, the precise function of ABI3 in human cancer and the potential signaling pathway and downstream effectors of ABI3 remain unclear." (PMID 21223585, 2011). "Additional studies will be required to verify whether PAK2 and/or Rho and Rac small GTPases are affected by ABI3 expression in other cancer subtypes and to identify other mediator of cell motility." (PMID 21223585, 2011). "Therefore, we tested whether FAT10 mediates phosphorylated ABI3-induced cancer cell migration using a wound-healing assay." (PMID 36926204, 2023). "However, it is still unclear whether phosphorylation of ABI3 contributes to cancer development and how the phosphorylated form of ABI3 is regulated." (PMID 36926204, 2023). "This approach could potentially guide drug selection based on the expression of ABI3 in cancer." (PMID 37942289, 2023). "Among the deregulated proteins, we identified known cancer proteins, such as the tumor suppressors ASS1 and ABI3, which were downregulated in our model, or specifically upregulated TRBC1." (PMID 41715231, 2026). "We showed that FAT10 mediates phosphorylated ABI3-induced cancer cell migration, probably through preferential interaction of FAT10 with phosphorylated ABI3." (PMID 36926204, 2023). "Further research is necessary to fully understand the interaction between phosphorylated ABI3 and FAT10 in the regulation of cancer progression." (PMID 36926204, 2023). "A prior investigation has demonstrated that members of ABI are crucial for synapse formation, suggesting that the specific relationship between ABI3 and synaptic vesicle-related activity in LGG cancer enrichment results warrants further exploration." (PMID 37942289, 2023). "To investigate the correlation between ABI3 expression levels and prognosis, we conducted a survival analysis, including OS, DSS, DFI, and PFS, for each cancer type." (PMID 37942289, 2023). "According to ESTIMATE, ABI3 expression manifested a positive correlation with stromal scores, immune scores, and ESTIMATE scores in the TME of 33 cancers, indicating that ABI3 was an important player in the immune response to cancer." (PMID 37942289, 2023).
cancer (continued). "Our results demonstrated that ABI3 expression manifested a positive correlation with the infiltration levels of CD4+ T cells, CAFs, Endo, HSCs, γ/δ T cells, NK T cells, Tregs, B cells, monocytes, and CD8+ T cells in the majority of the TCGA cancers." (PMID 37942289, 2023). "In four types of cancer (COAD, LGG, SARC, and UCEC), there was a positive correlation between ABI3 and TMB, and in two types of cancer (COAD and KIRC), there was a positive correlation between ABI3 and MSI." (PMID 37942289, 2023). "In most tumors, except for LIHC and KICH, the expression of ABI3 exhibit negatively correlated with the expression of MMR genes, suggesting that ABI3 may reduce TMB and MSI through the MMR system in certain cancers, such as BRCA." (PMID 37942289, 2023). "In contrast, it has been suggested that phosphorylation of ABI3 may disrupt inactive WRC formation, which may lead to cancer development through the activation of WRC." (PMID 36926204, 2023). "As hypermethylation of ABI3 might occurs in a cancer- and tissue-specific manner, we search for putative transcription factors binding sites (TFBS) in the R1 region of ABI3 gene." (PMID 27036019, 2016). "Therefore, our results suggest that FAT10 stabilizes the phosphorylated form of ABI3, which may lead to WRC activation, thereby promoting cancer cell migration." (PMID 36926204, 2023). "Our correlation analysis of ABI3 and immunoreactive genes across cancers demonstrated a positive relationship between ABI3 expression and genes related to immunoregulation, including MHC, immune activation, immunosuppressive, chemokine, and chemokine receptor proteins, in nearly all cancer types." (PMID 37942289, 2023).
neurodegenerative disease (2 papers, 2018 to 2025). A disorder of the central nervous system characterized by gradual and progressive loss of neural tissue and neurologic function. "Identification of association with disease status in other neurodegenerative diseases may aid in understanding the mechanism by which ABI3 and PLCG2 contribute to disease pathophysiology." (PMID 30326945, 2018). "An issue with microglial genes was also raised in a study evaluating ABI family member 3 (ABI3) and phospholipase C gamma 2 (PLCG2) missense variants as neurodegenerative disease risk factors among Caucasians and African Americans." (PMID 40362170, 2025). "Although these findings require replication in larger cohorts, they suggest distinct effects of the microglial genes, ABI3 and PLCG2 in neurodegenerative diseases that harbor significant vs. low/no amyloid ß pathology." (PMID 30326945, 2018).
ABI3 also shares sentences with these, for which no sentence is quoted: Hypertension (2 papers); ischemic heart disease (2); angina (1); autoimmune disease (1); eosinophilic esophagitis (1); follicular thyroid adenoma (1); inflammation (1); mental disorder (1); multiple system atrophy (1); neurological disorders (1); non-small cell lung carcinoma (1); progressive supranuclear palsy (1).